PANX1 (pannexin 1)
Diseases named in the same sentence as PANX1 in open-access papers (continued):
Sharing a sentence is not in itself a finding about the gene and the disease.
neuroblastoma (8 papers, 2012 to 2025). Neuroblastoma (NB) is the most common solid, extracranial childhood tumor. "More recently, our group confirmed this Panx1-actin association with endogenous Panx1 immunoprecipitations from a neuroblastoma cell line." (PMID 24409119, 2014). "Additionally, in high-risk neuroblastoma, inhibition of Panx1 channels using carbenoxolone and probenecid halted cell proliferation and reduced tumor growth, highlighting the therapeutic potential of Panx1 blockade in this pediatric cancer." (PMID 40978734, 2025). "Here, we identify that adenosine triphosphate (ATP) triggers macropinocytosis in murine Neuro2a neuroblastoma cells, driving an increase in cell size, and internalizing the ATP release channel pannexin 1 (PANX1) to macropinosomes." (PMID 41250870, 2025). "We first tested the impact of pre-treatment with amiloride (1 h; 300 μM) or vehicle (DMSO) on ATP-induced internalization of PANX1-EGFP constitutively expressed in murine neuroblastoma N2a cells using an analysis paradigm established in our previous studies." (PMID 41250870, 2025). "The mouse neuroblastoma cell line, N2a, expresses endogenous Panx1 as evidenced by q-PCR and immunocytochemistry." (PMID 38100403, 2023). "Subsequent studies on neuroblastoma cells have further revealed that treatment with MβCD interferes with ATP-induced Panx1 internalization, implying a role of cholesterol-rich domains in the process." (PMID 36291086, 2022). "Using gene ontology (GO) analysis we determined that 10% of the mass spectrometry-identified putative Panx1 interactors in neuroblastoma cells fell under a cytoskeleton classification." (PMID 24409119, 2014). "PANX1 is widely understood to promote tumour cell survival in various cancers, including the proliferation and differentiation of murine neuroblastoma and malignancy of human neuroblastoma." (PMID 41250870, 2025). "Taken together, these results suggest that, in addition to undergoing macropinocytosis in response to extracellular ATP, PANX1 could also play a broader role in the regulation of ATP-regulated macropinocytosis to promote expansion of neuroblastoma cell size." (PMID 41250870, 2025). "Our model involved generating stable expression of PANX1-EGFP in murine neuroblastoma N2a cells." (PMID 41250870, 2025). "In light of the significance of cholesterol in the organization and function of membrane proteins, we monitored the effect of the specific cholesterol depletion agents MβCD and lovastatin on the lateral diffusion parameters of Panx1 in N2a neuroblastoma cells and in primary cultures of astrocytes." (PMID 36291086, 2022). "The mouse N2a neuroblastoma cell line expressed endogenous Panx1, as evidenced by immunostaining." (PMID 36291086, 2022). "We manipulated pannexin 1 expression and activity in Neuro2a neuroblastoma cells and primary postnatal neurosphere cultures to demonstrate that pannexin 1 regulates neural stem and progenitor cell proliferation likely through the release of adenosine triphosphate (ATP)." (PMID 22458943, 2012). "Here we combine studies in the Neuro-2a (N2a) murine neuroblastoma-derived cell line as model NSC/NPCs, and VZ NSC/NPCs in vitro and in vivo, to elucidate the role of Panx1 in postnatal neuronal development." (PMID 22458943, 2012). "PANX1 W74A, which disrupts the ATP-dependent interaction with P2X7R and downstream internalization, eliminated the increase in mouse neuroblastoma N2a cell size triggered by extracellular ATP." (PMID 41250870, 2025). "In our previous studies, we identified that PANX1 is internalized in response to elevated extracellular ATP via an undetermined non-canonical endocytic mechanism in murine neuroblastoma cells." (PMID 41250870, 2025). "Finally, AEA uptake by PC3 prostate cancer and SH-SY5Y neuroblastoma cells, which express functional Panx1 channels, was not inhibited by carbenoxolone." (PMID 31110238, 2019).
neuroblastoma (continued). "In addition, we have investigated whether or not Panx1 inhibition affects the uptake of AEA into human PC3 prostate cancer cells and into both undifferentiated and differentiated SH-SY5Y neuroblastoma cells, since these are known to express functionally active Panx1 channels." (PMID 31110238, 2019).
viral infections (8 papers, 2021 to 2025). "In concordance, Panx1 HCs have been implicated in several viral infections, such as HIV infection of human primary cells." (PMID 39990207, 2025). "Furthermore, Panx1-mediated ATP release has been associated with viral infections, replication, and pathogeneses." (PMID 35628472, 2022). "Thus, targeting Panx-1 opening could have minimal side effects in healthy individuals and prevent viral infection and spread generated by multiple SARS-CoV-2 variants." (PMID 34841222, 2021). "For instance, in experimental models, pharmacological inhibition of Panx1 decreased extracellular ATP levels, a key molecule in exacerbated inflammatory signaling, improving survival under viral infection conditions." (PMID 40978734, 2025). "Our results strongly suggest that an increase in Panx1 HC activity plays a fundamental role in the initial phase of viral infections, particularly when dsRNAs are present." (PMID 39990207, 2025). "The upregulation of both oxidative phosphorylation genes and pannexin-1 in infected T cells suggests an important role for these processes in the immune response to viral infections." (PMID 37325659, 2023). "In viral infections, SARS-CoV-2, hCoV-229E, or HIV activate Panx1 hemichannels via CD4/CXCR4 CD4/CCR5, causing an outflow of ATP, which induces the maturation of IL-1ß through the activation of P2X7 receptors." (PMID 36699007, 2022). "However, the contribution of ATP and Panx-1 channels to inflammation and viral infections is still under investigation." (PMID 40740680, 2025). "Thus, the interplay between viral infection, channels activation including Panx-1 channels, ATP, and purinergic activation are essential for HIV infection and replication." (PMID 40740680, 2025). "Similar interactions between Panx-1 and purinergic receptors have been described in multiple lung functions such as blood pressure control, vasodilation/constriction, airway defense, and viral infection." (PMID 34841222, 2021). "However, beyond Panx1 HC, it remains to be determined whether other members of the proposed signaling pathway are involved in prevalent viral infections, such as SARS-CoV-2 infection." (PMID 39990207, 2025). "Interestingly, ATP release through Panx-1 channels may have more far-reaching implications than just as a marker for viral infection or future disorders." (PMID 34841222, 2021). "Probenecid has been shown to modify ACE2 expression in normal human lung tissue, the expression of the pannexin 1 (PANX1) gene regulating inflammation, and the host responses to virus infection." (PMID 40305196, 2025). "Using a murine model with T cell-specific Panx1 deletion, researchers observed a decrease in the frequency of effector and memory CD8+ T cells following viral infections." (PMID 40978734, 2025).
gout (7 papers, 2013 to 2025). A condition characterized by painful swelling of the joints, which is caused by deposition of urate crystals. "For example, Probenecid is an FDA-approved drug to treat gout and is an excellent Panx-1 blocker, as demonstrated in our previous studies." (PMID 34841222, 2021). "Probenecid (PBN), a drug that has been used for gout treatment, is a potent PANX1 inhibitor and is among several compounds that have been reported to effectively block PANX1 channel activity." (PMID 31817827, 2019). "Probenecid, a classic pharmacological agent for gout, has also been used historically in combination therapy with antibiotics to prevent cellular drug efflux and has been reported to inhibit Panx1." (PMID 23700432, 2013). "The Panx1 inhibitor probenecid is already FDA approved to treat gout with few side effects." (PMID 40697804, 2025). "Moreover, probenecid, which is a clinically used drug for gout and inhibits pannexin 1, attenuated ASC-speck formation." (PMID 35616535, 2022). "In our previous work, we employed to block Pannexin-1 channel in mice a drug Probenecid that is employed in clinic to increase uric acid excretion in gout patients that in addition possess some additional effect as Pannexin-1 channel inhibitor, and we noticed impaired G-CSF-mediated mobilization." (PMID 32533388, 2020). "Particularly with regard to the fact that the PANX1 inhibitors Prb and Cbx are already FDA-approved drugs used against gouty arthritis and tracheal ulcers, respectively." (PMID 35563450, 2022). "A mainstay treatment for gout, probenecid has been shown to function by inhibition of membrane transporters including those for organic anions (OAT), drug efflux and more recently, pannexin 1 (Panx1)." (PMID 23700432, 2013).
status epilepticus (7 papers, 2011 to 2024). Status epilepticus is defined as a continuous seizure lasting more than 30 min, or two or more seizures without full recovery of consciousness between any of them. "Using pharmacological tools and two transgenic mice deficient for Panx1 we show here that interference with Panx1 ameliorates the outcome and shortens the duration of kainic acid-induced status epilepticus." (PMID 21949881, 2011). "Using various approaches and Panx1-deleted mice, Panx1 channels (from glia and/or neurons) were proposed to contribute to status epilepticus in vivo." (PMID 29066951, 2017). "Evidence that Panx1 is activated during epileptiform activity was obtained by measuring the influx of YoPro1 in hippocampal slices from juvenile P13–14 mice in which status epilepticus (SE) was induced by i.p. injection of kainic acid (KA: 3.6 mg/kg)." (PMID 21949881, 2011). "In summary, our results provide the first direct evidence that Panx1 channels worsen seizures and sustain status epilepticus in vivo." (PMID 21949881, 2011). "In accordance with our results, Panx1 is overexpressed in different cell types from epileptic tissue, and their blockade with mefloquine reduced seizure severity and duration in kainate-induced status epilepticus." (PMID 30542266, 2018). "Our results indicate that Panx1 channels are opened by elevated K+ concentration and following kainic acid-induced status epilepticus and that blockade or deletion of Panx1 reduces the amount of ATP that is released and improves the behavioral manifestation of seizures." (PMID 21949881, 2011). "Alternatively or in addition, it is also possible that the reduced release of ATP from Panx1-null mice could also limit the activation of excitatory P2X receptors and thus the progression of status epilepticus." (PMID 21949881, 2011). "Moreover, that Panx1-mediated ATP release is an important event that contributes to prolong hyperexcitabilty is provided from our results showing that suppression of Panx1 channels ameliorates the behavioral manifestations of status epilepticus." (PMID 21949881, 2011). "To examine these issues, we used Panx1 transgenic mice, with global and cell-type specific Panx1 knockout, to evaluate the cognitive and behavioral consequences of ELS using the kainic acid (KA)-induced status epilepticus (SE) model." (PMID 39024558, 2024).
colon cancer (6 papers, 2016 to 2025). "And Carbenoxolone was proved to inhibit colon cancer cells' growth by inhibiting pannexin-1." (PMID 33776762, 2021). "Given the importance of AEA, PEA, 2-AG and Panx1 in the gut, we have investigated the effect of pharmacological inhibition of Panx1 upon the uptake, release and hydrolysis of AEA, and upon the uptake of PEA and 2-AG into human T84 colon cancer cells." (PMID 31110238, 2019). "Moreover, P2X7R antagonists and Panx1 inhibitors, Erioglaucine and 10Panx peptide reverts neuropathic pain caused by oxaliplatin, while Panx1 inhibitors do not interfere the cytotoxic effect of oxaliplatin on human colon cancer cells HT-29." (PMID 29865195, 2018). "In colon cancer cells that express liver X receptors (LXRs), P2X7 receptors and Panx1, it was proposed that the LXR ligand would bind its receptor and facilitate LXR’s association with Panx1." (PMID 27229305, 2016).
prostate carcinoma (6 papers, 2014 to 2025). A carcinoma that arises from epithelial cells of the prostate gland. "In prostate cancer cells Panx1 forms Ca2+ channels in the ER mediating the Ca2+ release from intracellular stores." (PMID 25237296, 2014). "Another possibility to explain this intracellular localization is that PANX1 may form Ca2+-permeable channels in the endoplasmic reticulum as observed in prostate cancer cells." (PMID 29882918, 2018). "On the subcellular level, a focused ultrasound (FUS) that has an amplitude of 46 MHz (12 Vp–p), pulse repetition of 1 kHz frequency, and duty of 5% cycle, stimulates ICWs in PC-3 prostate cancer cells via mechanosensitive pannexin-1 (PANX1) channels in the ER without cytoskeletal dependence." (PMID 40507332, 2025). "This signaling pathway is independent of the cytoskeletal integrity in invasive PC-3 prostate cancer and HEK 293T human embryonic kidney cells and critically relies on both PANX1 and IP3R for ICW initiation and propagation." (PMID 40507332, 2025).
Anxiety (5 papers, 2012 to 2024). Intense feelings of nervousness, tension, or panic often arise in response to interpersonal stresses. "Previous studies using a different Panx1-deficient mouse (Panx1−/−) revealed that loss of Panx1 leads to enhanced anxiety and impaired object recognition and spatial memory." (PMID 29692709, 2018). "The physiological modification, promoted by loss of Panx1, led to distinct behavioral alterations, enhancing anxiety and impairing object recognition and spatial learning in Panx1−/− mice." (PMID 23284764, 2012). "Loss of Panx1 promoted distinct behavioral changes, enhancing anxiety and impairing object recognition and spatial learning in Panx1−/− mice." (PMID 23284764, 2012). "The absence of Panx1 was recently shown to increase long-term potentiation (LTP) along with behavioral alterations, including increases in anxiety as well as spatial and recognition impairments, suggesting that Panx1 modulates synaptic plasticity and is needed for proper learning." (PMID 25360084, 2014). "Neither Panx1 nor ELS influenced thigmotaxis (a proxy for anxiety-like behavior), locomotor activity, and repetitive behaviors." (PMID 39024558, 2024). "Given that no overall deficits in locomotor activity and thigmotaxis were recorded in saline- or KA-injected adult mice of all genotypes, our results indicate that neither Panx1 nor ELS lead to anxiety-like behavior." (PMID 39024558, 2024). "Transgenic animals lacking the Panx1 gene display an enhanced hippocampal LTP accompanied by behavioral alterations including increased anxiety, impaired object recognition and spatial memory deficits." (PMID 29692709, 2018).
colorectal cancer (5 papers, 2021 to 2025). A primary or metastatic malignant neoplasm that affects the colon or rectum. "In murine models of colorectal cancer, Panx1 inhibition resulted in a significant reduction in the immune response induced by chemotherapy, whereas the administration of an ATP analog enhanced therapeutic efficacy." (PMID 40978734, 2025). "Here, we show that TNFα sensitizes colorectal cancer promote the release of ATP by caspase-8/3-mediated PANX1 cleavage via TNFR1 during chemotherapy-induced cell death." (PMID 38195677, 2024). "In the present study, we found that TNFα promoted PANX1 cleavage through TNFR1 in a caspase 3-dependent manner in colorectal cancer." (PMID 38195677, 2024). "Taken together, our results indicated that chemotherapy sensitizes colorectal cancer to release ATP via the caspase-8/3-mediated cleavage of PANX1 downstream of TNFα." (PMID 38195677, 2024). "Here, we demonstrated that TNFα-mediated PANX1 cleavage was essential for ATP release in response to chemotherapy in colorectal cancer (CRC)." (PMID 38195677, 2024). "We then evaluated the clinical relevance of PANX1 in colorectal cancer patients who received adjuvant chemotherapy." (PMID 38195677, 2024). "However, recent study has shown that Panx1 is significantly elevated in colorectal cancer, and inhibiting Panx1 can obstruct tumor cell proliferation and tumor growth." (PMID 40909173, 2025). "However, the mechanisms underlying this PANX1-ATP-P2RX7 axis in colorectal cancer have not been described." (PMID 38195677, 2024). "In colorectal cancer cells, TNF-α modulates Panx1 activation to promote ATP release." (PMID 40978734, 2025).
glaucoma (5 papers, 2014 to 2023). Increased pressure in the eyeball due to obstruction of the outflow of aqueous humor. "Panx1 is a cell surface mechanosensory Ca2+-permeable channel protein implicated in the pathophysiology of RGCs in retinal ischemia–reperfusion injury and glaucoma." (PMID 37998361, 2023). "Our results also suggest that OFF-type RGCs exhibit particularly high Panx1 channel activity, which can also underlie their susceptibility to glaucoma." (PMID 29643381, 2018). "If the same is true for post-ischemic RGCs, this result suggests that the selective death of the Panx1-enriched RGCs as a feasible explanation of the early decrease in PERG amplitude typically observed in glaucoma and retinal ischemia." (PMID 29643381, 2018). "Kurtenbach and colleagues also review in “Emerging functions of pannexin 1 in the eye” how Panx1 is involved in processing visual information, as well as its role in different pathological conditions such as hypoosmotic stress and glaucoma." (PMID 26528132, 2015). "Combined with a recent reports showing that distinct RGC subtypes that project dendrites into the OFF lamina are selectively affected in glaucoma, our finding of a high Panx1 activity in OFF-type neurons suggests a role of Panx1-mediated toxicity in glaucoma RGC pathology." (PMID 29643381, 2018). "Evidence is accruing that Panx1 might be directly involved in the pathology of glaucoma." (PMID 25309318, 2014). "Importantly, the neuroprotective effect of transient Panx1 blockade provides feasibility for the pharmacological modulation of this channel as a part of a prophylactic or therapeutic intervention in acute and chronic ocular hypertension injury, including glaucoma." (PMID 29643381, 2018).
inflammatory bowel disease (5 papers, 2014 to 2025). A spectrum of small and large bowel inflammatory diseases of unknown etiology. "Panx1 plays an important role in mediating gut function and in the pathophysiology of Inflammatory Bowel Disease (IBD)." (PMID 40646589, 2025). "Although Panx1 and P2X7R are implicated in the process of inflammation and cell death, few studies have looked at the role they play in inflammatory bowel disease in human." (PMID 30127744, 2018). "Thus, Panx1 and P2X7R may have roles in causing mucosal damage, a common clinical feature of inflammatory bowel disease." (PMID 30127744, 2018). "Another human disease involving Panx-1 hemichannels is inflammatory bowel diseases (IBD) including ulcerative colitis, and Crohn's disease." (PMID 24672487, 2014). "Pannexin-1 (Panx1) channels allows the passage of messenger molecules, such as adenosine triphosphate (ATP), which in turn activate the P2X7 receptors (P2X7R) that regulate inflammation and cell death in inflammatory bowel diseases." (PMID 36072579, 2022).